METTL3 (methyltransferase 3, N6-adenosine-methyltransferase complex catalytic subunit)
Diseases named in the same sentence as METTL3 in open-access papers (continued):
Sharing a sentence is not in itself a finding about the gene and the disease.
infection (continued). "Parental, negCtrl and METTL3 KO 293 T cell lines were infected with recombinant EBOV expressing firefly luciferase from an additional transcriptional unit, and reporter activity was measured one day post infection." (PMID 37306620, 2023). "In both METTL3- and METTL14-depleted Caco-2 cells, RNA-sequencing and qRT-PCR revealed upregulated immune response genes following infection (including IL-6, IL-8, CCL20, CXCL1, and CXCL3), while IFN and interferon-stimulated genes (ISGs) remained largely unaffected." (PMID 37509095, 2023). "(c) Immunoblot of T47D cells infected with retrovirus encoding shMETTL3 resistant pMSCV-METTL3 without tag or control vector followed by METTL3 shRNA or control shRNA infection." (PMID 37589705, 2023). "In this study, we identify METTL3 as a negative suppressor for global innate immune signaling cascades in response to infection of RNA virus Vesicular Stomatitis Virus (VSV) in vitro and in vivo." (PMID 33707441, 2021). "By contrast, in PBS mock infection, only 299 upregulated and 199 downregulated genes were detected and most of ISGs expression were not changed in Mettl3-depleted RAW264.7 cells." (PMID 33707441, 2021). "However, METTL3, METTL14, WTAP, ALKBH5, and FTO were all present in both the nucleus and cytoplasm after infection." (PMID 34225491, 2021). "Therefore, the timely application of melatonin during early stages of infection may positively regulate YTHDF2 and negatively regulate METTL3 to inhibit viral replication." (PMID 35897696, 2022). "After METTL3 or WTAP knockout, the splicing efficiency of the protein encoded by the E1A gene expressed early during infection did not change, while the splicing efficiency of the protein encoded by the fiber gene expressed late in infection decreased significantly." (PMID 34368152, 2021). "To assess whether METTL3 is localized in EBOV inclusion bodies, we performed immunofluorescence analyses of cells infected with a recombinant EBOV expressing a C-terminally flagHA-tagged NP and stained the cells one day post infection for NP, VP30 and endogenous METTL3." (PMID 37306620, 2023). "When cells were pre-treated with LMB, both the M protein and METTL3 failed to translocate to the cytoplasm, even during BPIV3 infection." (PMID 41325422, 2025). "We noted a slight decrease in METTL3 and METTL14 protein levels at 36 h post-infection (hpi), whereas the protein levels of FTO and ALKBH5 did not significantly change during CVB3 infection." (PMID 39339923, 2024). "Coinciding with their NP-binding abilities, the full-length METTL3, ΔNTD, and ΔMTD, rather than ΔZFD, were able to enhance SFTSV infection, indicating that ZFD-mediated METTL3-NP interaction is indispensable for augmented SFTSV lifecycle." (PMID 39585899, 2024). "The results showed that the protein levels of METTL3, METTL14, and YTHDF2 did not change significantly in A549 cells during infection by influenza virus WSN/1933." (PMID 35583334, 2022). "Zika virus (ZIKV) replication efficiency was enhanced after METTL3 or METTL14 knockdown, modifying its host mRNA landscape, whereas the hepatitis C virus (HCV) infection rate was increased, not through viral RNA replication but through increased production of infectious viral particles." (PMID 33431045, 2021).
cardiovascular diseases (14 papers, 2021 to 2025). "Actually, several reports have uncovered the regulatory impact of Mettl3 deficiency on mitochondria in cardiovascular diseases." (PMID 38169612, 2024). "Currently, research on m6A methylation detection in cardiovascular diseases primarily focuses on the expression of METTL3 and FTO." (PMID 40005339, 2025). "METTL3, an RNA methyltransferase enzyme, exerts therapeutic effects on various cardiovascular diseases." (PMID 38169612, 2024). "It is worth noting that our understanding of METTL3's role in cardiovascular diseases is still developing, and further investigations are needed to elucidate the underlying mechanisms and potential therapeutic implications." (PMID 38169612, 2024). "METTL3 is constitutively active and its activity is largely regulated by the expression levels in the development of cardiovascular diseases." (PMID 36980863, 2023). "Recent works have shown that METTL3 can be regarded as a potential biomarker in diagnosis or treatment in cardiovascular diseases." (PMID 36980863, 2023). "In fact, similar contradictory results regarding the role of METTL3 have been observed in other cardiovascular diseases." (PMID 35836108, 2022). "Inhibition of METTL3 or targeting of m6A methylation might be a potential strategy for intervention in cardiovascular diseases." (PMID 35844806, 2022). "METTL3 is the core catalytic enzyme in m6A and is involved in a variety of cardiovascular diseases." (PMID 35836108, 2022). "Given that RNA m6A levels are significantly elevated in patients with cardiovascular diseases such as AD, inhibitors of METTL3 may have a wide range of applications in this field." (PMID 35844806, 2022). "In recent years, many studies have revealed the critical roles of m6A methylation in cardiovascular diseases, which were exemplified by abnormal levels of m6A modification as a result of methyltransferases (writer, Mettl3, and Mettl14) and demethylases (eraser, ALKBH5, and FTO)." (PMID 35004673, 2021). "Also, we demonstrated that METTL3 knockdown could inhibit angiogenesis in vitro and in vivo, providing a potential therapeutic method for cardiovascular diseases." (PMID 34950654, 2021). "The dynamic changes in the expression and activity levels of METTL3 and METTL14, as well as the m6A demethylase FTO, can serve as potential biomarkers for cardiovascular diseases." (PMID 40005339, 2025). "METTL3 and METTL14 are known as core components of the methyltransferase complex, with METTL3 functioning as a catalytic subunit, while METTL14 being responsible for substrate recognition, and they play a pivotal role in cardiovascular diseases." (PMID 36093141, 2022). "Since that time, m6A methylation has been extensively studied, and its functions, mechanisms, and effectors (e.g., METTL3, FTO, METTL14, WTAP, ALKBH5, and YTHDFs) in various diseases, including cardiovascular diseases, have rapidly been investigated." (PMID 34221238, 2021). "Accumulating data have shown METTL3′s negative effects on cardiovascular diseases." (PMID 36980863, 2023).
metabolic disorders (13 papers, 2020 to 2025). "METTL3-mediated m6A methylation destabilizes mRNA of metabolism-related genes, leading to metabolic disorders and lipid accumulation in the liver." (PMID 40094566, 2025). "Studies have demonstrated that METTL3-mediated m6A methylation destabilizes the mRNA of metabolism-related genes, contributing to metabolic disorders and lipid accumulation in the liver." (PMID 40094566, 2025). "METTL3-mediated m6A methylation makes the metabolism-related gene’s mRNA more unstable, leading to metabolic disorders and lipid accumulation in the liver." (PMID 36157445, 2022). "Our findings reveal a critical role of Mettl3-mediated m6A in HFD-induced metabolic disorders and hepatogenous diabetes." (PMID 33160098, 2020). "In contrast, hepatocyte-specific knockout of Mettl3 significantly alleviated HFD-induced metabolic disorders by slowing weight gain, reducing lipid accumulation, and improving insulin sensitivity." (PMID 33160098, 2020). "To confirm the relationship between high expression level of Mettl3 and HFD-induced metabolic disorders, we specifically overexpressed Mettl3 in mouse liver by hepatocyte-targeted AAV8 and hepatocyte-specific promoter (LP1)." (PMID 33160098, 2020). "Therapeutic strategies targeting m6A modification can regulate the onset of metabolic diseases by influencing macrophage metabolic changes, for instance, small molecule inhibitors of methyltransferase-like 3 (METTL3) can affect glucose metabolism and inhibit IBD." (PMID 40066451, 2025). "Taken together, m6A level and its methyltransferase Mettl3 were consistently up-regulated in the liver of HFD mice, indicating that Mettl3-mediated m6A methylation might be involved in metabolic disorders induced by HFD." (PMID 33160098, 2020). "Furthermore, the expression levels of m6A modification‐associated proteins, such as METTL3 and FTO, in the blood may also be indicative of metabolic disease onset, thereby providing auxiliary diagnostic value." (PMID 40066222, 2025). "Here, we unveil a previously unrecognized METTL14/METTL3/G6pc mRNA m6A/YTHDF1 and YTHDF3/G6pc biosynthesis/HGP pathway governing HGP in health and metabolic disease." (PMID 40278833, 2025). "Here, we showed that both Mettl3 expression and m6A level increased in the livers of mice with high fat diet (HFD)-induced metabolic disorders." (PMID 33160098, 2020). "A series of methylases are involved in the development of metabolic diseases; among them, FTO was found to play a pivotal role in promoting disease, YTHDC2 was believed to suppress disease development, while the role of METTL3 and METTL14 in metabolic disease still needs to be further investigated." (PMID 40066222, 2025). "Consistently, it has been shown that METTL3 expression and overall mRNA m6A methylation level was upregulated in the livers of mice with high fat diet (HFD)-induced metabolic disorders, while hepatocyte-specific knockout of METTL3 alleviated lipid accumulation and improved insulin sensitivity." (PMID 33611339, 2021).
hematological malignancies (10 papers, 2019 to 2025). "METTL3 has a high structural similarity to DNA methyltransferase, and azacytidine is a DNA demethylation drug that has been approved for the treatment of hematologic malignancies." (PMID 40171845, 2025). "This is in line with former findings that METTL3 speeds up the progression of hematological malignancies." (PMID 38665846, 2024). "STC-15 and UZH1a both serve as METTL3 inhibitors with potential clinical application value in hematological malignancies." (PMID 38665846, 2024). "Similar to FTO inhibitors, METTL3 inhibitors have been produced and studied in recent years, and they will be a potent potential target to treat patients with hematological malignancies in the future, especially AML and chemoresistant CML." (PMID 35574332, 2022). "Notably, mutations in spliceosomal genes such as SF3B1, U2AF1, SRSF2, ZRSR2, and the RNA-stabilizing methyltransferase METTL3 are specifically enriched in haematological disease." (PMID 40495353, 2025). "Further studies on the regulatory mechanisms of METTL3 in hematological diseases are required." (PMID 37280654, 2023). "Therefore, we summarized the function of METTL3 in normal hematopoiesis and several hematological malignancies." (PMID 35574332, 2022). "Therefore, we will mainly focus on the role of METTL3 in normal hematopoiesis and hematological neoplasms in the present review and discuss directions for future research and potential clinical applications of METTL3 in hematological diseases." (PMID 35574332, 2022). "From the analysis on the “Total” data set IGF2BP1, ALKBH5, IGF2BP2, RBM15, METTL3, ZNF217 is the potentially carcinogenic gene in hematological malignancies." (PMID 33816257, 2021).
gastrointestinal tumors (8 papers, 2021 to 2026). "The RNA methyltransferases associated with ncRNAs in digestive system tumors are METTL3, METTL14, WTAP, and FTO." (PMID 37781524, 2023). "However, most studies in this area have focused on gastrointestinal tumors, and the cause of abnormal METTL3 expression in PCa remains unclear." (PMID 38166703, 2024). "This article provides a comprehensive review of the involvement of Mettl3 in gastrointestinal tumors." (PMID 41517663, 2026). "Understanding the intricate role of Mettl3 in gastrointestinal tumor pathogenesis holds promise for the development of targeted therapies and personalized treatment strategies." (PMID 41517663, 2026). "This comprehensive review highlights the pivotal role of the methyltransferase Mettl3 in mediating m6A modification across gastrointestinal tumors." (PMID 41517663, 2026). "Specifically, we found that LPS-induced upregulation of METTL3 and m6A modification in mice led to severe colon inflammation through activation of the TLR4/NF-κB-mediated inflammatory pathway in macrophages." (PMID 38725850, 2024). "The effect of METTL3, an important “writer”, has been extensively studied in gastrointestinal tumors." (PMID 36335087, 2022). "In contrast, in gastrointestinal tumors, METTL3 is mainly responsible for oncogenic effects." (PMID 37344779, 2023). "Besides, other studies have shown that METTL3 plays an essential role in gastrointestinal tumors." (PMID 33976730, 2021).
heart disease (7 papers, 2019 to 2025). "Fat mass and obesity-associated protein (FTO), an N6-methyladenosine (m6A) demethylase, and methyltransferase-like 3 (METTL3), an m6A methyltransferase, are pivotal regulators in the methylation landscape associated with heart diseases." (PMID 39334823, 2024). "It is believed that the m6A modification regulates the primary factor called methyltransferase-like 3 (METTL3), which is directly connected to cardiac disease progression." (PMID 36233177, 2022). "This study provides evidence that m6A methylation is dynamically regulated during human and murine cardiac disease and highlights an important role of the m6A methylase Mettl3 in regulating cardiac growth by gene expression control." (PMID 30967445, 2019). "Additionally, accumulating evidence showed that the m6A level is closely related to the development of heart disease; for example, METTL3 overexpression can induce eccentric remodeling and cardiac dysfunction alone without an additional stressor." (PMID 35858921, 2022). "Thus, we hypothesized that the PI3K‐Akt pathway plays a key role in the regulation of radiation‐induced heart disease by METTL3." (PMID 40471098, 2025).
kidney disease (7 papers, 2021 to 2025). "METTL3 is reported to be closely associated with kidney diseases, such as renal ischemic reperfusion injury and DKD." (PMID 40421968, 2025). "Dysregulation of m6A modification has been linked to a variety of kidney diseases, Particularly, METTL3 is the N6‐adenosine‐methyltransferase complex catalytic subunit (70 kDa)." (PMID 40421968, 2025). "Moreover, METTL3 is more closely associated with kidney disease than METTL14 and FTO, although there are already related drugs to improve renal function and treat renal diseases through METTL3, more in-depth research and exploration can be carried out in this aspect in the future." (PMID 38066436, 2023). "METTL3, an important m6A methylase that has been widely studied in kidney disease, was further examined in the kidney." (PMID 39261902, 2024). "RNA m6A modification and activation of METTL3 have been suggested to be major mediators of kidney diseases in models other than TGF-β-induced and UUO kidney fibrosis." (PMID 38297163, 2024). "Recent studies indicate Mettl3's role in renal disease progression." (PMID 40765834, 2025). "There are currently 24 known m6A regulatory proteins, but studies on m6A methylation in kidney disease have been limited to four to five enzymes such as METTL14, METTL3 and FTO, and there have been few studies on other enzymes." (PMID 38066436, 2023). "However, we also observed the alteration of other major m6A modifying enzymes, such as METTL3 and FTO, in proteinuric kidney disease models." (PMID 34580283, 2021). "METTL3, METTL14 and FTO may play major roles in interstitial fibrosis during UUO nephropathy." (PMID 38066436, 2023).
neurological diseases (6 papers, 2021 to 2025). "This review suggested that METTL3 may be a potential diagnostic biomarker and treatment target for neurological diseases." (PMID 37189411, 2023). "METTL3, a pivotal methyltransferase, is widely recognized for its critical involvement in m6A methylation and signalling regulation in various neurological diseases." (PMID 41154582, 2025). "METTL3, as a classical methylase, has been proved to be involved in progressive neurological diseases." (PMID 36977205, 2023). "Furthermore, the module genes were screened based on their association with METTL3, implying a possible molecular network of METTL3-mediated methylation modifications and energy metabolism with neurological diseases." (PMID 37373264, 2023). "Thus, mapping the roles and mechanisms of METTL3 in regulating nervous system events would be helpful for both the clinical diagnosis and treatment of neurological diseases." (PMID 37189411, 2023).
bacterial infection (5 papers, 2022 to 2024). "All these results suggest that DDX5/METTL3/METTL14-mediated m6A modification suppresses the TLR2/4/NF-κB-mediated inflammatory signaling pathway in vivo during bacterial infection." (PMID 38182816, 2024). "Moreover, our findings ultimately verify that DDX5 blocks an inflammatory response after bacterial infection via METTL3-mediated m6A modification." (PMID 38182816, 2024). "Therefore, we employed Mettl3 cKO mice to verify the role of DDX5/METTL3-mediated m6A machinery during bacterial infection in vivo." (PMID 38182816, 2024). "However, whether the same DDX5/METTL3-mediated m6A machinery also regulates TLR2/4/NF-κB-mediated inflammatory responses during bacterial infection was unclear." (PMID 38182816, 2024). "We therefore aimed to evaluate the possibility of DDX5 forming a complex with METTL3 and METTL14 during bacterial infection." (PMID 38182816, 2024). "Methyltransferase-like 3 (METTL3) regulates immunity and inflammatory responses induced by the bacterial infections in animals." (PMID 36555481, 2022). "In the absence of bacterial infection, DDX5 forms a complex with METTL3 and METTL14, which regulates target transcripts, including TLR2/4 mRNAs, through m6A modification." (PMID 38182816, 2024). "We discovered that under normal conditions (i.e., without bacterial infection), DDX5 interacts with two known m6A writer proteins, METTL3 and METTL14, to form a ternary m6A writer complex, which recognizes and binds to TLR2/4 mRNAs to introduce m6A modifications." (PMID 38182816, 2024).
inflammation (5 papers, 2023 to 2025). Aberrant reaction of the microcirculation characterized by movement of fluid and leukocytes from the blood into extravascular tissues. "The in vivo experiments also revealed that the promotion effect of METTL3 on lung inflammation was reversed by miR-192-5p inhibitor in asthmatic mice." (PMID 39867638, 2025). "METTL3 exacerbates LPS-induced pulmonary inflammation by mediating m6A methylation of STAT2 mRNA to enhance its stability and translation, thereby activating inflammatory responses and aggravating lung injury." (PMID 41105618, 2025). "In addition, the depletion of macrophages completely reversed the susceptibility of Mettl3 KO mice to allergic airway inflammation, compared with wild-type animals, suggesting that the vital role of METTL3 in airway inflammation is dependent on macrophages." (PMID 37957139, 2023). "To further confirm the expression of METTL14, WTAP, METTL3, FTO and ALKBH5 in NPC tissues, we utilized RT‐qPCR to detect their expression in 28 NPC tissues and 7 nasopharyngeal chronic inflammation tissues." (PMID 39021049, 2024).
adenocarcinoma (4 papers, 2021 to 2023). A common cancer characterized by the presence of malignant glandular cells. "The suppression of METTL3 in adenocarcinomas reduced the expression of adenocarcinoma-specific markers and significantly increased apoptosis." (PMID 35682599, 2022). "Analysis of METTL3 mRNA expression alterations revealed that ~32% of adenocarcinoma samples possessed altered METTL3 mRNA expression, with 79/498 cases (~15%) having low METTL3 expression, and 85/498 cases (~17%) possessing elevated METTL3." (PMID 36291932, 2022).